C10orf143 (chromosome 10 open reading frame 143)
Synonyms: LINC00959
Gene: Protein-coding gene on chromosome 10 (130,020,025 to 130,110,840, reverse strand). Ensembl gene ENSG00000237489.
Homologues: Orthologues: chimpanzee C10orf143 (98% identical), macaque C10orf143 (81% identical), guinea pig C10orf143 (62% identical), pig C10orf143 (60% identical), rabbit C10orf143 (58% identical), rat C1h10orf143 (58% identical), mouse 9430038I01Rik (57% identical).
Diseases named in the same sentence as C10orf143 in open-access papers:
C10orf143 is named in the same sentence as 6 diseases in open-access papers, as found by Europe PMC text mining. Sharing a sentence is not in itself a finding about the gene and the disease. The quoted sentences say what the papers report.
liver cancer (1 paper, 2022). An epithelial or non-epithelial malignant neoplasm that arises from the liver. "In Europeans, C10orf143 had a lower proportion of Neanderthal introgression among liver cancer patients compared to the general population and in East Asians, NENF and TEDC1 showed a similar pattern." (PMID 36503519, 2022). "After correcting for multiple testing, there was one gene with a significant depletion of Neanderthal introgression in European liver cancer patients compared to non-affected individuals—C10orf143 (p-value = 7.12 × 10–12, adjusted p-value = 2.40 × 10–8)." (PMID 36503519, 2022).
C10orf143 also shares sentences with these, for which no sentence is quoted: colon cancer (2 papers); tumor (2); breast carcinoma (1); lung adenocarcinoma (1); non-small cell lung carcinoma (1).